BRCA1 (BRCA1 DNA repair associated)
Diseases named in the same sentence as BRCA1 in open-access papers (continued):
Sharing a sentence is not in itself a finding about the gene and the disease.
triple-negative breast carcinoma (continued). "BRCA1 carriers were more likely to be triple negative breast cancer compared to BRCA2 carriers." (PMID 34490083, 2021). "Pathogenic germline mutations in BRCA1, BRCA2, PALB2, RAD51C, and RAD51D, all of which are involved in the HR pathway, are known to confer high or moderate penetrance susceptibility to ovarian and/or triple-negative breast cancer." (PMID 34635660, 2021). "The value of platinum-based adjuvant chemotherapy in patients with triple-negative breast cancer (TNBC) remains controversial, as does whether BRCA1 and BRCA2 (BRCA1/2) germline variants are associated with platinum treatment sensitivity." (PMID 32789480, 2020). "BRCA1 mutation carriers have a higher risk of developing triple-negative breast cancer (TNBC), which is a refractory disease due to its non-responsiveness to current clinical targeted therapies." (PMID 32591500, 2020). "In addition, this miRNA was found to have an important role in triple negative breast cancer progression by disrupting the BRCA1." (PMID 32854743, 2020). "SNAIL1 expression is high in low BRCA1 triple negative breast cancer." (PMID 32194804, 2020). "Triple negative breast cancer (TNBC) may have diverse defects in HR DNA repair, through germline mutations in BRCA1, BRCA2 and PALB2, somatic mutations in BRCA1 and BRCA2, promoter methylation of BRCA1 and RAD51C, and other as yet to be identified mechanisms." (PMID 32471999, 2020). "We investigated the frequency of BRCA1 promoter hypermethylation in 237 triple-negative breast cancers (TNBCs) from a population-based study using reported whole genome and RNA sequencing data, complemented with analyses of genetic, epigenetic, transcriptomic and immune infiltration phenotypes." (PMID 32719340, 2020). "For interest in understanding mechanism involved in the development of triple negative breast cancer (TNBC), we chose to further examine how IQGAP1 might influence BRCA1 because it is both a centrosome marker and is associated with TNBC." (PMID 32655836, 2020). "In triple-negative breast cancers, ATR inhibitors are highly efficient in patient-derived xenografts that have a BRCA1 mutation or that exhibit the BRCA-like phenocopy when combined with irinotecan, a clinically approved topoisomerase 1 inhibitor that causes double-stranded breaks." (PMID 32997669, 2020). "Germline BRCA1/2 prevalence is relatively low in sporadic triple-negative breast cancer (TNBC)." (PMID 30630526, 2019). "The triple negative subtype appeared to be a part of the BRCA genetic testing criteria; however, the proportion of patients with triple negative breast cancer in those with an L63X and BRCA1 positive status in our study was much higher than that in those who were BRCA 1/2 negative." (PMID 31143373, 2019). "Given its role in regulating Rad51 proteolysis in cells lacking BRCA1, Emi1 was identified as a regulator of PARPi sensitivity in BRCA1-deficient triple-negative breast cancer." (PMID 31632280, 2019). "Here we analyzed the role of β‐hCG in BRCA1 defective triple negative breast cancer." (PMID 29460395, 2018). "More recently in a clinical trial in triple-negative breast cancer, no benefit was observed for carboplatin in subjects with tumor-associated BRCA1 methylation, compared with BRCA1/2 mutation." (PMID 30266954, 2018). "Our study has identified for the first time that β‐hCG expression is linked to BRCA1 status and its over expression is seen in BRCA1 mutated (5382insC) but not in wild type triple negative breast cancer cells." (PMID 29460395, 2018). "In addition, one VUS characterized as an in-frame deletion in exon 23 of BRCA1 gene (c.5425_5430delGTTGTG), was observed in a patient with positive family history, diagnosed with triple negative breast cancer." (PMID 29854292, 2018).
triple-negative breast carcinoma (continued). "It would be interesting to design studies in the future to assess the influence of the combinatorial dietary regimen and compare their effects in ER positive, ER negative and BRCA1 mutated triple negative breast cancers." (PMID 29899271, 2018). "We studied 197 triple-negative breast cancers: 78 (39.6%) from BRCA1 mutation carriers and 119 (60.4%) from noncarriers." (PMID 28721372, 2016). "In sporadic triple-negative breast cancers, BRCA1 is frequently inactivated at the transcriptional level, and it has been shown that BRCA1 inactivation may be due to methylation of its promoter brought about by ID4." (PMID 26392359, 2015). "BRCA1 gene expression is frequently down-regulated in triple-negative breast cancers." (PMID 26392359, 2015). "In sporadic triple-negative breast cancers BRCA1 is frequently inactivated at the transcriptional level, and it has been reported that this inactivation may be brought about by promoter methylation." (PMID 26392359, 2015). "We hypothesized that the identification of miRNAs targeting the 3′-UTR of BRCA1 might be used to uncover miRNAs involved in the development of triple-negative breast cancers." (PMID 26392359, 2015). "Second, we did not analyze the results according to the triple-negative breast cancer subtype or BRCA1 mutation status." (PMID 25608004, 2015). "Interestingly, we note that overexpression of LSD1 correlates with down-regulation of BRCA1 in triple negative breast cancer." (PMID 25679396, 2015). "The BRCA1 gene plays a key role in triple negative breast cancers (TNBCs), in which its expression can be lost by multiple mechanisms: germinal mutation followed by deletion of the second allele; negative regulation by promoter methylation; or miRNA-mediated silencing." (PMID 26490435, 2015). "BRCA1 promoter methylation was observed almost exclusively in triple negative breast cancer." (PMID 25475740, 2014). "This supports the idea that this miR could behave specifically in triple negative breast carcinoma subtype and could act alone independently of other micro-RNAs since it targets BRCA1 gene." (PMID 25369070, 2014). "This case report highlights the necessity of genetic testing even when family history is not prominent, at least for BRCA1 mutations, of young females diagnosed with triple negative breast cancer." (PMID 24660075, 2014). "Likewise, mutations in BRCA1, BRCA2, PALB2, and other components with the HR pathway are common in familial and certain subtypes of sporadic breast cancer, particularly triple negative breast cancer (91–, 93)." (PMID 24062981, 2013). "Absence of estrogen-signaling, BRCA1 deficiency, high mitotic activity, hypoxia and invasiveness are hallmarks of the basal 1 subtype of triple negative breast cancer." (PMID 24260093, 2013). "BRCA1 and BRCA2 mutation carriers are frequently diagnosed with triple-negative breast cancer." (PMID 22666503, 2012). "This study did not check for BRCA1/2 mutation status; only 20% of triple-negative breast cancers exhibit these mutations." (PMID 21989215, 2011). "In this study, we estimate the proportion of BRCA1 mutation carriers among women diagnosed at age 40 or younger with triple-negative breast cancer, without a significant family history of cancer." (PMID 19298662, 2009). "However, patients with triple-negative breast cancer with first onset at 61 years of age or older are also likely to have germline variants in BRCA1, indicating that the risk is not low." (PMID 40323562, 2025). "We tested the growth inhibitory effects of Tala with and without Deci in this cell line panel, using the triple negative breast cancer cell line SUM149PT as a control with a naturally occurring pathogenic BRCA1 2288delT mutation in a different genetic background." (PMID 39819384, 2025).
triple-negative breast carcinoma (continued). "The mechanisms of action of eribulin and platinum drugs are different, and previous studies have not compared the effects of eribulin and platinum drugs as salvage therapy in recurrent metastatic triple-negative breast cancer, with or without BRCA1/2 gene mutations." (PMID 38481526, 2024). "We collected a case of familial triple negative breast cancer without BRCA1/2 pathogenic variation." (PMID 39138583, 2024). "Therefore, we analysis the correlation between TRIM47 and BRCA1 in triple-negative breast cancer." (PMID 36906594, 2023). "Notably, no specific distribution of BRCA1/2 variants was observed regarding triple negative breast cancer (TNBC) or patient gender status." (PMID 35858847, 2022). "In order to understand whether genes involved in NAD+ metabolism, other than PARP1, might be synthetic lethal with BRCA-gene defects, we carried out parallel siRNA screens in isogenic BRCA1-defective and BRCA1-proficient triple-negative breast cancer cell lines." (PMID 34750509, 2021). "TQ treatment, which increases the expression of BRCA1 in triple-negative breast cancer cells through an unknown mechanism, was also recently found to induce a significant decrease in the expression of G9a in Jurkat cells and in breast cancer cells, in parallel with the upregulation of several TSGs." (PMID 33922029, 2021). "Nolan and colleagues showed that in BRCA1-mutated triple-negative breast cancers (TNBCs), both mutational loads and the numbers of TIL significantly increased with the accompanying elevation of PD-1 and CTLA4 expression compared to those in the BRCA1-wild type one." (PMID 31023256, 2019). "The reason for the homologous repair defect in most of these tumors remains unknown, but BRCA1 promoter methylation has been reported in 30-35% of all triple negative breast cancers with germline BRCA1/2 wild-type status, in particular among tumors of the basal-like subtype." (PMID 31225507, 2019). "One explanation might be that these probes, located in the BRCA1 gene promoter upstream to the transcription site, differ from the ones whose methylation was inversely correlated with BRCA1 expression in the TCGA and triple-negative breast cancer patients." (PMID 29872499, 2018). "Emerging evidence has shown that adding poly(ADP-ribose) polymerase (PARP) inhibitors to chemotherapy regimens is superior to the control regimens alone in BRCA1-mutated triple-negative breast cancer (TNBC) patients, but their underlying mechanisms have not been fully elucidated." (PMID 28176879, 2017). "Finally, the TNT trial did not identify further biomarkers, in addition to BRCA1/2 germline mutation, for carboplatin benefit in patients with metastatic triple-negative breast cancer." (PMID 28725277, 2017). "However, a significant portion of triple-negative breast cancer patients does not carry BRCA1 mutations." (PMID 27413552, 2016). "Platinum-based chemotherapy has been considered as a candidate for the treatment of triple-negative breast cancer related to their BRCA1 phenotype, and our results suggest that cisplatin used alone or combined with other drugs could be used to treat triple-negative cells." (PMID 26284587, 2015). "Epigenetics may play an important role in ER-negative breast cancer susceptibility as well: Hypermethlyation of BRCA1 has been found to be associated with triple negative breast cancer but not ER-positive breast cancer." (PMID 25389105, 2014). "However, a significant portion of triple-negative breast cancer patients do not carry BRCA1 mutations." (PMID 23405268, 2013). "The fact that attenuated expression of HSF1 and BRCA1 proteins were associated with the apoptotic effects of WA in both MDA-MB-231 and BT20 cells suggests that they may play a role in the anticancer action of WA in triple negative breast cancer cell lines." (PMID 25969759, 2012).
triple-negative breast carcinoma (continued). "Furthermore, studies have demonstrated disruption of BRCA1 through epigenetic and other regulatory mechanisms, which may occur in sporadic cases of basal-like or triple-negative breast cancer." (PMID 24281106, 2010). "To test this we selectively targeted the BRCA1 and BRCA2 loci in the HRR proficient triple negative breast cancer cell line MDA-MB-231 (M231wt), using standard CRISPR-Cas9 techniques to generate an isogenic cell line panel." (PMID 39819384, 2025). "The data includes three cell lines MCF10A (normal), MDA-MB-231 (triple negative breast cancer), and HCC1937 (triple negative breast cancer with BRCA1 mutant) with either hydroxyurea treatment (TR) or untreated (UT) samples." (PMID 39041914, 2024). "CDK12 inhibitors reversed de novo and acquired resistance to PARPis in BRCA1 mutant and BRCA wild-type triple negative breast cancer cells." (PMID 37892162, 2023). "In this study, we investigated the occurrence of the BRCA1 c.-107A > T SNV in 178 patients, most of them with triple-negative breast cancer, who tested positive for BRCA1 promoter hypermethylation by MLPA in their breast or ovarian tumor." (PMID 36112334, 2023). "Triple-negative breast cancers (TNBC) frequently harbor defects in DNA double-strand break repair through homologous recombination (HR), such as BRCA1 dysfunction." (PMID 36906594, 2023). "PI3K inhibition is also sufficient to reduce BRCA1 and BRCA2 expression, hampering HR repair in triple-negative breast cancer." (PMID 37370140, 2023). "In this study, we presented the fundamental role of BRCA1 interactors BRIP1 and RAD50 in the development of differential severity in triple-negative breast cancer (TNBC) among various affected individuals." (PMID 36873936, 2023). "Histopathological subtypes were triple-negative breast cancer (TNBC) (n = 49, 42 in BRCA1 pV carriers), endocrine sensitive (n = 41), and Her2 positive (n = 9)." (PMID 36011268, 2022). "Liquiritigenin, on the other hand, has been shown to prevent carcinogenesis in triple-negative breast cancer cells (MDA-MB-231 and BT549) by enhancing breast cancer 1 (BRCA1) transcriptional activity and reducing DNA methyltransferase (DNMT) activity." (PMID 35740057, 2022). "TNBCs (triple negative breast cancers, ER-, PR-, and HER2-) were more commonly found in carriers with BRCA1, BRCA2 or PALB2 PVs." (PMID 35135604, 2022). "It has been proposed that the interactions between BRCA1-IRIS overexpressing cells and mesenchymal stem cells (MSCs) result in faster growing metastatic triple-negative breast cancers (TNBC)." (PMID 35008272, 2021). "In another study, neoadjuvant chemotherapy was associated with a higher rate of pathological complete response in BRCA1 and BRCA2 carriers than in other patients with triple-negative breast cancer." (PMID 32939053, 2020). "To further validate our previous findings, we selected three different human triple negative breast cancer (TNBC) cell lines, representative of different BRCA and HRR status —Hs578T and MDA-MB-468 as BRCAwt and HCC1937 as BRCA1 mutant." (PMID 32630796, 2020). "In triple-negative breast cancer, the expression level of NUSAP1 was found to be significantly correlated with BRCA1 expression and higher expression of NUSAP1 led to poor prognosis while positive BRCA1 was related to improved outcomes." (PMID 31729978, 2019). "NUSAP1 expression was correlated with BRCA1, BRCA2, and BARD1 expression, and upregulation of NUSAP1 predicted poor prognosis in triple-negative breast cancer." (PMID 30678687, 2019). "It is not limited to triple negative breast cancer cells, as β-hCG expression was induced in MCF7 upon BRCA1 knockdown." (PMID 28869585, 2017).
triple-negative breast carcinoma (continued). "We therefore analyzed the relationship between BRCA1 and LSD1 protein level in our set of triple negative breast cancer samples." (PMID 25679396, 2015). "We next determined the effects of treatment with the PS or VS on the expression levels of the DNA damage response and on the DNA repair proteins in the triple negative breast cancer cells lines SUM159PT (BRCA1 wild-type) and HCC1937 (BRCA1 mutant)." (PMID 25026298, 2014). "In summary, we report here that WA causes denaturation and proteasome-dependent degradation of HSF1 and BRCA1 proteins in MDA-MB-231 and BT20 triple-negative breast cancer cells." (PMID 25969759, 2012). "In the present study, we intended to examine the effects of WA on BRCA1 and HSF1 protein expression in MDA-MB-231 and BT20 triple-negative breast cancer cells as potential mechanisms of its anticancer action." (PMID 25969759, 2012). "Additionally, hsa-miR-199a-3p downregulates BRCA1, impairing DNA repair and enhancing sensitivity to cisplatin and PARP inhibitors in triple-negative breast cancer (TNBC)." (PMID 41154751, 2025). "Due to the abundant usage of chemotherapy in young triple-negative breast cancer (TNBC) patients, the unbiased prognostic value of BRCA1-related biomarkers in this population remains unclear." (PMID 38191387, 2024). "We chose HCC1937 cells, a triple-negative breast cancer cell line lacking BRCA1, but not sensitive to any known PARP-i." (PMID 38682589, 2024). "The PrECOG0105 phase 2 trial showed that the LOH test identified patients with triple-negative breast cancer with a high LOH (≥10%) score, and lacking BRCA1/2 mutation, who achieved a favorable pathologic response to iniparib in combination with chemotherapy." (PMID 37173992, 2023). "The patient harboring this BRCA1 PV had no family history of the disease and was initially diagnosed with triple-negative breast cancer (TNBC) at age 48, stage IIA." (PMID 38028594, 2023). "To extend our investigations into a more clinically relevant context, we tested the effect of IFNβ treatment on pancreatic adenocarcinoma cells (CAPAN-1) and triple-negative breast cancer cells (SUM149PT and MDA-MB-436) carrying BRCA1 or BRCA2 defects and we invariably obtained the same result." (PMID 37783689, 2023). "A dual PARP and RAD51 inhibitor might as well re-sensitize triple-negative breast cancer (TNBC) cells with hereditary and acquired defects in the BRCA1 pathway after development of PARP inhibitor resistance reconstituting the HR machinery." (PMID 34356606, 2021). "For the molecular subtype, more triple-negative breast cancers were found in patients with GPVs in BRCA1 and other CPGs than the non-carriers (68.6% and 26.8% vs. 14.9%, p=4.7×10-42 and 0.01)." (PMID 34336698, 2021). "Although not significant, tumors having biallelic BRCA1 inactivation tended to have more advanced (T2–T4) (P = 0.09) and triple-negative breast cancer (P = 0.55)." (PMID 33067557, 2020). "Furthermore, de novo intrachromosomal genomic BRCA1 rearrangements and promoter demethylation leading to re-expression of BRCA1 have been demonstrated in PDX models and post-treatment biopsies of triple-negative breast cancer patients, respectively." (PMID 35582591, 2019). "That was the case for BRCA1, ERBB2 and ERBB3 loci that were found to be deregulated in triple-negative breast cancers or von Hippel-Lindau (VHL) tumour suppressor gene and PRCC that was linked to clear cell renal cell carcinoma and papillary renal cell carcinoma respectively." (PMID 31105870, 2019). "The PARP1 inhibitor olaparib combines well with DNA damaging treatments and other chemotherapies and shows combination effects with selinexor in triple negative breast cancers cells independent of BRCA1 status." (PMID 28467801, 2017).